NOD2 (nucleotide binding oligomerization domain containing 2)
Diseases named in the same sentence as NOD2 in open-access papers (continued):
Sharing a sentence is not in itself a finding about the gene and the disease.
kidney cancer (5 papers, 2017 to 2022). Primary or metastatic malignant neoplasm involving the kidney. "We observed that in kidney cancer patients, the incidence of the NOD2 variant appeared to be lower in the group aged between 60 and 70 years, however, this was not statistically significant." (PMID 35478773, 2022). "The NOD2 c.3020insC variant was detected in 7,3% of the kidney cancer patients, a similar frequency as found in the Polish population." (PMID 35478773, 2022). "In the present analysis, no enough evidence was promulgated to authenticate the existing association between NOD2 and kidney cancers." (PMID 29254180, 2017). "We previously reported that the common founder mutation in NOD2 may be more common in patients with bladder cancer and be associated with a reduced susceptibility to kidney cancer but these preliminary findings required further confirmation." (PMID 35478773, 2022). "Thus, the NOD2 c.3020insC or the CDKN2A p.A148T polymorphism cannot be added to the list of genes that are associated with an increased susceptibility to bladder or kidney cancer at this time." (PMID 35478773, 2022). "Materials and Methods: We compared the allele frequencies of NOD2 c.3020insC and CDKN2A p.A148T allele in 706 patients with bladder cancer, 410 cases with kidney cancer against two control groups." (PMID 35478773, 2022). "Then, we reanalyzed all the data in order to make a conclusion about the relationship between NOD2 gene and the prognosis of kidney cancer patients." (PMID 29254180, 2017). "In order to collect more information about the NOD2 gene in kidney cancers and find out the reason for the result of KIRP, we use SurvExpress to put stratification of 468 samples into practice according to death, grade, stage, and pathology." (PMID 29254180, 2017). "Although some clinical trials had been taken to investigate the role of immunotherapy for kidney cancer patients, scarcely any trials were involved in NOD2 genetic status." (PMID 29254180, 2017). "Previously, most of us paid our attention to the relationship between NOD2 and common cancers except for kidney cancers." (PMID 29254180, 2017). "In order to conclude the role of NOD2 among kidney cancer patients, we downloaded the published data and made further analysis with the help of some online tools." (PMID 29254180, 2017). "We clearly stated the close relationship between the NOD2 gene and tumor stage on the survival of kidney cancer patients by deeper stratification analysis." (PMID 29254180, 2017). "To ensure that our original findings were not erroneous and indeed represented the actual frequency found in bladder and kidney cancer patients, we re-evaluated the frequency of the NOD2 c.3020insC allele and the p.A148T polymorphism in CDKN2A among 706 bladder cancer and 410 kidney cancer patients." (PMID 35478773, 2022). "Nucleotide-binding oligomerization domain-containing protein 2 (NOD2) may play an important role in the outcome of kidney cancer patients." (PMID 29254180, 2017). "In the future, with the increase in kidney cancer patients data and the development of science, more and more unknown relevance of NOD2 gene may be elucidated." (PMID 29254180, 2017). "Therefore, we tried to reanalyze the data online to make sure the role of NOD2 in kidney cancer patients." (PMID 29254180, 2017). "Our reanalysis of data stated clearly that the NOD2 gene may have something to do with the survival of kidney cancers." (PMID 29254180, 2017). "The status of NOD2 gene maybe a biomarker for the survival of kidney cancer patients." (PMID 29254180, 2017). "I deduced that the emergence of such results may be related to limited samples assigned to different groups.The deeper analysis results of the fourth database also showed the inclination that the NOD2 expressive level was an unfavorable signal for the survival of kidney cancer patients." (PMID 29254180, 2017). "However, the relationship between NOD2 and kidney cancer patients was poorly understood." (PMID 29254180, 2017).
laryngeal carcinoma (5 papers, 2014 to 2025). Carcinoma that arises from the laryngeal epithelium. "NOD2 alterations may also be a predisposing factor for cancer development, such as laryngeal carcinoma, that may worsen patient outcomes by compounding the disease burden of leukemia." (PMID 38361685, 2024). "NOD2/CARD15 connects to chromosome 16q12, which also can be a marker for a poorer prognosis in laryngeal carcinoma." (PMID 38361685, 2024).
liver cirrhosis (5 papers, 2010 to 2017). "The key inclusion criterion is the presence of a NOD2 risk variant in patients with decompensated liver cirrhosis." (PMID 25887140, 2015). "Recently common variants of nucleotide-binding oligomerization containing domain 2/caspase recruitment domain 15 (NOD2/CARD15) linked to impaired mucosal barrier function were also reported to be risk factors for spontaneous bacterial peritonitis in liver cirrhosis." (PMID 20886039, 2010).
mastitis (5 papers, 2015 to 2025). Inflammation of breast tissue during lactation or postpartum due to an obstructed duct or infection. "Their findings demonstrated a significant correlation between NOD2 polymorphism, mastitis incidence, and 305-day milk production." (PMID 40428307, 2025). "Association analysis of polymorphic loci of the NOD2 with mastitis in dairy cows showed significant differences in the allele frequencies of the polymorphic loci." (PMID 40427248, 2025). "SLC11A1 was closely associated with the expression of genes involved in the regulation of the immune response and inflammation, with S100A12, NOD2, TLR2 and SPI1 being closely associated with mastitis resistance." (PMID 40427248, 2025). "We predicted a protein interaction network involving SLC11A1 interacting with 10 proteins, of which SPI1, NOD2, TLR2 and S100A12 have been reported as candidate genes associated with mastitis resistance." (PMID 40427248, 2025). "The genes NOD2, CXCR1, SPP1 and LF, which are implicated in resistance to occult mastitis, were genotyped utilizing the efficient and cost-effective Kompetitive Allele-Specific PCR (KASP) technology." (PMID 40428307, 2025). "The present study aims to reveal the characteristics of TLR2, NOD2, and related cytokines in mammary glands against mastitis induced by S. aureus at an early stage in a rat mastitis model." (PMID 25990971, 2015). "The present study examined TLR2, NOD2, and related cytokines in mammary glands infection induced by S. aureus at early stages in a rat mastitis model." (PMID 25990971, 2015). "Finally, we predicted the SLC11A1 protein interaction network and found that SPI1, NOD2, TLR2 and S100A12 interacted with SLC11A1 and were reported as candidate genes associated with mastitis resistance." (PMID 40427248, 2025). "TLR2, NOD2, and inflammatory cytokines (TNF-α, IL-1β, IL-6, CXCL1, IL-10, TGF-β1, and IFN-γ) are involved in the response to mastitis induced by S. aureus." (PMID 25990971, 2015). "In the present study, genes NOD2, CXCL8, OAS2, and TLR4 were differentially expressed in the blood transcriptome of subclinical mastitis cows and involved in the NOD-like receptor, Toll-like receptor pathway and were identified as key candidates for this study." (PMID 36204322, 2022). "On the other hand, the direct association between mastitis and MBL1, MBL2, NOD2 and M-SAA3.2 genes has not been fully explored so far." (PMID 33535694, 2021). "TLR2 and NOD2 are important pathogen recognition receptors, but their functions have not been investigated in the context of early stages of mastitis." (PMID 25990971, 2015).
metabolic syndrome (5 papers, 2017 to 2022). A cluster of metabolic risk factors for CARDIOVASCULAR DISEASES and TYPE 2 DIABETES MELLITUS. "In contrast, there are human studies demonstrating highly upregulated expression of NOD1 and NOD2 in individuals with metabolic syndromes." (PMID 33503814, 2021). "Therefore, it is possible that NOD2 activation in KCs and DCs protects mice from hepatocarcinogenesis and metabolic syndrome, whereas NOD2 activation in hepatocytes promotes oncogenesis." (PMID 36268029, 2022). "Activation of NOD1 and NOD2 is involved in the development of metabolic syndromes." (PMID 36268029, 2022). "Although both NOD1 and NOD2 are expressed in adipose tissue, only NOD1 expression is elevated in obese patients, individuals with metabolic syndrome, or mice fed a HFD." (PMID 33503814, 2021).
necrotizing enterocolitis (5 papers, 2014 to 2023). Necrotizing enterocolitis (NEC) is a devastating disease that affects mostly the intestine of premature infants. "In humans, one study found a significant association between NOD2 loss-of-function mutations and an increased risk of necrotizing enterocolitis or focal intestinal perforation in very low-birth-weight infants, suggesting NOD2 deficiency is related to necrotic pathology in humans." (PMID 35418999, 2022). "Lastly, we examined whether there were any differences in the frequency of the polymorphisms of NOD2, CARD9, RAC1 and ATG16L1 in relation to inflammatory etiologies of IF such as in the cases with necrotizing enterocolitis (NEC)." (PMID 24465786, 2014). "Ligation of receptors of the innate immune system, including Toll-like receptors and the intracellular pathogen recognition receptor NOD2/CARD15 appear to be involved in the initiation of enterocyte apoptosis, which can destroy intestinal barriers and lead to necrotizing enterocolitis." (PMID 25926780, 2015). "Similarly, Nod2 stimulation reduces LPS-triggered TLR4 activation and is protective in a model of LPS-induced necrotizing enterocolitis." (PMID 25423082, 2014).
ovarian carcinoma (5 papers, 2014 to 2025). A malignant neoplasm originating from the surface ovarian epithelium. "In the Polish population, the NOD2 c.3020insC variant has been identified in colorectal, early-onset laryngeal, lung, ductal breast cancer in situ, ovarian cancers." (PMID 35478773, 2022).
steatosis (5 papers, 2015 to 2022). Increased lipid within the cytoplasm of cells. "In conclusion, the elucidation of the association between NOD1/NOD2-mediated signaling pathways and liver diseases opens new avenues for the development of novel treatments for hepatitis, steatosis, and HCC." (PMID 36268029, 2022). "Thus, one likely explanation for our data demonstrating the development of HFD-dependent hyperlipidemia, steatosis, and inflammation in Nod2−/− mice could be due the loss of Nod2-mediated activation of AMPK." (PMID 33239685, 2020). "HFD-fed NOD2−/− mice had increased liver-resident (F4/80+) macrophages and increased steatosis evident by histology (Fig4F) and higher TAGs (Fig4G)." (PMID 25666722, 2015).
abortion (4 papers, 2019 to 2023). the ending of pregnancy by removing a fetus or embryo before it can survive outside the uterus. "There is a lower level of NOD2 in decidual stromal cells from patients with unexplained recurrent spontaneous abortion than the normal pregnancy group, suggesting that a lower level of NOD2 is related to complex autoimmune disorder in humans." (PMID 36560538, 2022). "In addition, the NOD2 level in decidual stromal cell from females with unexplained recurrent spontaneous abortion is lower compared to normal pregnancy, suggesting that the NOD2 protein is required for sustaining normal pregnancy in humans." (PMID 36496806, 2022). "There is significantly higher mRNA and protein levels of NOD2 in DSCs from the normal pregnancy group than the unexplained recurrent spontaneous abortion group, suggesting that NOD2 is necessary for sustaining normal pregnancy in humans." (PMID 37228386, 2023). "Lack of NOD1 and NOD2 expression in macrophages was sufficient to recapitulate the increase in pup viability that we previously showed for B. abortus-infected Nod1−/− Nod2−/− mice, suggesting a cell-type-specific role for NOD1 and NOD2 in placentitis and abortion." (PMID 31337727, 2019). "However, NOD1/NOD2 knockout mice were not completely resistant to B. abortus-induced abortion, which prompted us to identify additional cellular pathways involved in triggering placental and fetal pathology." (PMID 31337727, 2019).
acute GVHD (4 papers, 2017 to 2025). "Notably, PAMPs such as lipopolysaccharide (LPS) and nucleotide-binding oligomerization domain containing 2 (NOD2) have been implicated in the pathogenesis of acute GVHD." (PMID 39840040, 2024). "Several recent studies in Caucasian patients have described a significant correlation between the severity of acute GVHD and the presence of three NOD2 SNPs: R702W, G908R, and L1007insC." (PMID 29165176, 2017). "All these factors are also involved in the pathophysiology of acute GVHD through various mechanisms, including regulating inflammation (NOD2), promoting inflammation (IL-17), inducing proliferation and interferon-γ (IL-23R), and amplifying and prolonging immune responses (MIF)." (PMID 41291248, 2025). "No dysfunctional NOD2 variants were found in the severe acute GVHD group that may explain the differences in the occurrence of acute GVHD among different ethnic populations." (PMID 29165176, 2017).
Behçet disease (4 papers, 2012 to 2021). "This study aimed to investigate whether single nucleotide polymorphisms (SNPs) of five NLR family genes (NOD1, NOD2, NLRP1, NLRP3 and CIITA) are associated with Behcet’s disease (BD) in a Chinese Han population." (PMID 26833430, 2016). "In Behcet's disease NOD2 and TLRs appear to serve as independent, pattern recognition receptor of unknown antigens." (PMID 22330585, 2012).
campylobacteriosis (4 papers, 2017 to 2020). Infections with bacteria of the genus campylobacter. "In the past few years, secondary abiotic as well as conventional NOD2 deficient IL-10−/− (NOD2−/− IL-10−/−) mice were used to unravel the role of the innate immune receptor nucleotide-oligonucleotide-domain 2 (NOD2) during campylobacteriosis and clearance of C. jejuni infection." (PMID 32231139, 2020). "Given that innate immune receptors including nucleotide-oligomerization-domain-2 (Nod2) are essentially involved in combating enteropathogenic infections, we here surveyed the impact of Nod2 in murine campylobacteriosis." (PMID 28592996, 2017). "Given that host innate immune responses are pivotal for combating enteropathogenic infections including campylobacteriosis, we here investigated the impact of Nod2 during C. jejuni infection of secondary abiotic mice lacking IL-10−/−." (PMID 28752081, 2017). "Based on the finding that nitroprusside attenuated murine campylobacteriosis the authors concluded that NOD2 is essential for pathogen control by bactericidal responses involving nitric oxide." (PMID 28127403, 2017). "Given that the innate immune receptor nucleotide-oligomerization-domain-2 (Nod2) is involved in clearance of enteropathogens, we here evaluated its role in murine campylobacteriosis." (PMID 28752081, 2017). "Following C. jejuni infection, secondary abiotic NOD2−/− IL-10−/− mice harbored the pathogen at high loads, but developed less severe enterocolitis as compared to IL-10−/− counterparts, indicating that NOD2 signaling increases the severity of campylobacteriosis." (PMID 32231139, 2020). "For instance, in IL-10−/− mice that had been pre-treated with antibiotics for 1 week, Nod2 was shown to be essential for controlling campylobacteriosis, given that Nod2−/− IL-10−/− mice exhibited an exacerbation of C. jejuni induced large intestinal inflammation." (PMID 28592996, 2017). "Taken together, these results confirm the down-regulation of TLR-4 signaling by NOD2 activation not only in IBD, but also in campylobacteriosis." (PMID 32231139, 2020). "A previous elegant in vivo study revealed that NOD2 is essential for the control of campylobacteriosis in antibiotics-treated mice lacking IL-10." (PMID 28127403, 2017).
Cirrhosis (4 papers, 2015 to 2021). A chronic disorder of the liver in which liver tissue becomes scarred and is partially replaced by regenerative nodules and fibrotic tissue resulting in loss of liver function. "Three of the five patients with NOD2 variants developed severe cirrhosis, and two of them underwent liver transplantation whereas deaths occurred only in three patients without NOD2 variants." (PMID 28765628, 2017). "Recently, NOD2 germline variants were found to be potential predictors of the development of infectious complications and mortality in patients with cirrhosis." (PMID 25887140, 2015). "In line with this, the NOD2 germline variants p.R702W, p.G908R and c.3020insC were found to be predictors of the development of infectious complications and mortality in patients with cirrhosis." (PMID 25887140, 2015).
cryopyrin-associated periodic syndrome (4 papers, 2014 to 2025). Cryopyrin associated periodic syndrome (CAPS) defines a group of autoinflammatory diseases, characterized by recurrent episodes of systemic inflammatory attacks in the absence of infection or autoimmune disease. "This includes two of the NLRP3 SNPs, R260W and D303N (NOD2 R334 and D382), which are associated with cryopyrin-associated periodic syndromes (CAPS) gain of function diseases Muckle–Wells syndrome and Neonatal Onset Multisystem Inflammatory Disease." (PMID 25093298, 2014).
depression (4 papers, 2021 to 2024). "Whereas NOD2 on our identified pleiotropic locus 16q12.1, as a recognition receptor in the NLR family, has been shown that mice deficient in NOD2 and NOD1 exert signs of stress anxiety and depression in the context of hypothalamic–pituitary–adrenal axis hyperactivity." (PMID 40226707, 2024). "In contrast to the conventional drug L-thyroxine for curing hypothyroidism, YJT has an efficacy for attenuating systematic inflammatory responses, related with depression in intestinal TLR4 and Nod2/Pglyrp1 signaling pathways." (PMID 37270649, 2023). "Regarding its implication with the hippocampus, NOD2, like NOTCH1, may be related to anxiety, as in the case of depression." (PMID 34072914, 2021).
enteritis (4 papers, 2018 to 2024). Inflammation of the small intestine. "Specifically, NOD2 was associated with CD (Regional enteritis, 555.1, P = 1.38 × 10−4 in UK Biobank and P = 2.56 × 10−2 in BioMe BioBank) and IBD (P = 4.49 × 10−2 in UK Biobank and P = 2.29 × 10−2 in BioMe BioBank)." (PMID 38741190, 2024). "The “NOD-like receptor signaling pathway” in the middle stages was coincident with enteritis related miRNA regulation for NOD2 signaling pathway." (PMID 30246797, 2018). "Thus, nucleotide-binding oligomerization domain 2 (NOD2) signal channel would be activated by MSCs to boost the cyclooxygenase-2 (COX-2) and PGE2 expression and reduce the multiplication of monocyte to ease enteritis." (PMID 30687760, 2018).
Glucose intolerance (4 papers, 2017 to 2023). Glucose intolerance (GI) can be defined as dysglycemia that comprises both prediabetes and diabetes. "Correlation studies found an association between NOD1 and NOD2 expression and glucose intolerance." (PMID 37239938, 2023). "In addition, one study reported that the NOD2 agonist MDP decreased adipose inflammation and glucose intolerance in obese mice, but did not induce changes in the gut microbiome composition." (PMID 32774333, 2020).
Hepatitis (4 papers, 2019 to 2025). Inflammation of the liver. "NOD2 has also been involved in hepatic inflammation diseases, as attested by its role in promoting hepatitis through inflammatory cytokines production, and it is common knowledge that hepatic inflammation is an important contributing factor to the development of HCC." (PMID 37149620, 2023).
hypothyroidism (4 papers, 2023 to 2025). Abnormally low levels of thyroid hormone. "In contrast to the conventional drug L-thyroxine for curing hypothyroidism, YJT has a unique efficacy for attenuating systematic inflammatory responses via the suppression of intestinal LPS–TLR4 and peptidoglycan–Nod2/Pglyrp1 signaling pathways." (PMID 37270649, 2023).